FBP1 (fructose-bisphosphatase 1)
Description:
Catalyzes the hydrolysis of fructose 1,6-bisphosphate to fructose 6-phosphate in the presence of divalent cations, acting as a rate-limiting enzyme in gluconeogenesis. Plays a role in regulating glucose sensing and insulin secretion of pancreatic beta-cells. Appears to modulate glycerol gluconeogenesis in liver. Important regulator of appetite and adiposity; increased expression of the protein in liver after nutrient excess increases circulating satiety hormones and reduces appetite-stimulating neuropeptides and thus seems to provide a feedback mechanism to limit weight gain.
Synonyms: FBP
Tractability: Small molecule: a structure with a bound ligand is known; a high-quality ligand is known; it has a high-quality binding pocket; it belongs to a druggable protein family. PROTAC: its protein half-life has been measured; a small molecule that binds it is known.
Target class: Enzyme; Phosphatase
Chemical probes: PD083175
Gene: Protein-coding gene on chromosome 9 (94,603,133 to 94,640,323, reverse strand). Ensembl gene ENSG00000165140.
Subcellular location (Human Protein Atlas): Mitochondria
Pathways (Reactome):
Chromatin organization: Interaction of NuRD complexes with transcription factors
Metabolism: Gluconeogenesis
Gene Ontology:
Molecular function: AMP binding; fructose 1,6-bisphosphate 1-phosphatase activity; identical protein binding; metal ion binding; protein binding; RNA polymerase II-specific DNA-binding transcription factor binding; monosaccharide binding; phosphatase activity; phosphoric ester hydrolase activity
Biological process: cellular response to magnesium ion; cellular response to xenobiotic stimulus; fructose 6-phosphate metabolic process; gluconeogenesis; negative regulation of cell growth; negative regulation of glycolytic process; negative regulation of Ras protein signal transduction; negative regulation of transcription by RNA polymerase II; regulation of gluconeogenesis; fructose metabolic process; carbohydrate metabolic process; cellular hyperosmotic salinity response; cellular hypotonic salinity response; cellular response to cAMP; cellular response to insulin stimulus; cellular response to phorbol 13-acetate 12-myristate; cellular response to raffinose; response to nutrient levels
Cellular component: cytoplasm; extracellular exosome; nucleus; cytosol; extracellular region
Genetic constraint (gnomAD): Loss-of-function variants: 24 observed, 29.19 expected, observed/expected ratio (o/e) 0.82, 90% interval 0.6 to 1.16. The upper end of that interval is the gene's LOEUF score, 1.16, which puts it in group 5 of 6, group 1 being the genes least tolerant of losing a copy. Missense variants: 345 observed, 459.67 expected, observed/expected ratio (o/e) 0.75, 90% interval 0.69 to 0.82. Synonymous variants: 175 observed, 183.56 expected, observed/expected ratio (o/e) 0.95, 90% interval 0.84 to 1.08.
Gene-disease validity (ClinGen):
ClinGen rates the evidence that FBP1 causes each of these diseases.
fructose-1,6-bisphosphatase deficiency (autosomal recessive): Definitive. Fructose-1,6-biphosphatase (FBP) deficiency is a disorder of fructose metabolism characterized by recurrent episodes of fasting hypoglycemia with lactic acidosis, that may be life-threatening in neonates and infants.
Homologues: Orthologues: chimpanzee FBP1 (99% identical), macaque FBP1 (98% identical), pig FBP1 (90% identical), rat Fbp1 (85% identical), mouse Fbp1 (85% identical), tropical clawed frog fbp1 (82% identical), rabbit FBP1 (66% identical), dog FBP1 (65% identical), Drosophila melanogaster fbp (63% identical), Caenorhabditis elegans fbp-1 (62% identical). Paralogues in human: FBP2 (77% identical).
Diseases named in the same sentence as FBP1 in open-access papers:
FBP1 is named in the same sentence as 137 diseases in open-access papers, as found by Europe PMC text mining. Sharing a sentence is not in itself a finding about the gene and the disease. The quoted sentences say what the papers report.
breast carcinoma (66 papers, 2010 to 2025). "On the one hand, the loss of FBP1 promotes tumor progression by enhancing glycolysis and accelerating cancer cells growth, thereby leading to a poor prognosis in patients with breast cancer, pancreatic cancer and liver cancer." (PMID 40419474, 2025). "In basal-like breast cancer cells, the Snail-G9a-Dnmt1 complex is essential for silencing the E-calmodulin promoter and is also the cause of methylation of FBP1." (PMID 40100307, 2025). "In a study that followed previous studies, we found a strong association between high FBP1 expression and good prognosis in several cancers, such as lung, liver, kidney, and breast cancer." (PMID 35404841, 2022). "Analyzing TIGAR expression according to breast cancer subtypes, we found that TIGAR is increased in the FBP1-loss basal-like subtype of breast cancer." (PMID 32927665, 2020). "Loss of FBP1 expression was associated with poor survival and was strongly related to palindromia after tamoxifen treatment in patients with breast cancer." (PMID 29556139, 2018). "On the other hand, TGF-β-mediated activation of EMT increased the stemness and tumorigenic activities of basal-type breast carcinoma cells through loss of fructose-1, 6-biphosphatase (FBP1) and the consequent activation of pyruvate kinase M2." (PMID 28686632, 2017). "This metabolic rewiring enhanced CSC-like features and promoted tumorigenicity of breast cancer cells, making the loss of FBP1 a critical oncogenic event in EMT and metastatic potential of breast cancer cells." (PMID 29403375, 2017). "Loss of Fbp1 also represses reactive oxygen species (ROS) production in breast cancer." (PMID 33960626, 2021). "Importantly, the loss of FBP1 also promoted the CSC-like phenotype in the breast cancer cells by increasing the interaction of Wnt signaling molecules β-catenin and transcription factor t-cell factor (TCF)." (PMID 31552162, 2019). "FBP1 is a rate-limiting enzyme in gluconeogenesis, and its loss seems to be a critical oncogenic event in epithelial-mesenchymal transition-promoted basal-like breast cancer cell progression." (PMID 28262837, 2017). "FBP1 is increasingly identified as a tumor suppressor as loss of FBP1 expression has been shown to promote tumor progression by enhancing aerobic glycolysis, thereby resulting in poor prognosis in patients with clear cell renal cell carcinoma, breast cancer and hepatocellular carcinoma." (PMID 38834617, 2024). "The metabolic changes due to FBP1 loss could increase tumorigenicity of breast cancer cells." (PMID 28262837, 2017). "HMGB2 promotes LDHB expression and inhibits FBP1 expression, which in turn promotes breast cancer growth via boosting the Warburg effect." (PMID 40100307, 2025). "Snail-mediated inhibition of FBP1 loss provides a metabolic advantage for Basal-Like breast cancer (BBC), and the loss of FBP1 is a critical oncogenic event in epithelial-mesenchymal transition and BBC." (PMID 39588377, 2024). "In the context of breast cancer, FBP1 augments the ubiquitination of Notch1 via the Fbw7 pathway, subsequently leading to its degradation by the proteasome." (PMID 38349431, 2024).
breast carcinoma (continued). "Specifically, FBP1 inhibits the potential Warburg effect by counteracting glycolytic flux in clear cell renal cell carcinoma, breast cancer, lung adenocarcinoma, hepatocellular carcinoma, and prostate cancer." (PMID 38349431, 2024). "FBP1, a gluconeogenesis regulatory enzyme, has been found modulate cell proliferation and chemosensitivity by targeting c-myc in breast cancer." (PMID 36880837, 2023). "Previous research demonstrated that FBP1 expression was significantly lower in basal‐like breast cancer (BLBC) and that loss of FBP1 induced glycolysis and glucose uptake and inhibited oxygen consumption and reactive oxygen species production under hypoxia." (PMID 36525508, 2023). "In triple-negative breast cancer, CELF6 up-regulates the expression of FBP1 by stabilizing the mRNA expression of FBP1 and suppresses the development of breast cancer." (PMID 35910766, 2022). "Studies have shown that FBP1 can inhibit the malignant progression of cancers such as hepatocellular carcinoma, cholangiocarcinoma, and breast cancer." (PMID 36050791, 2022). "In breast cancer, studies have indicated that FBP1 is suppressed by Snail in basal-like breast cancer but contributes to triple-negative breast cancer progression." (PMID 35404841, 2022). "The G9a-Snail-DNMT1 complex also silences fructose bisphosphatase 1 (FBP1) expression in basal-like breast cancer." (PMID 35740522, 2022). "In basal-like breast cancer and other cancer types, reduced Fructose-1,6-bisphosphatase (FBP1) expression, is due to FBP1 promoter methylation." (PMID 34631530, 2021). "In basal-like breast cancer, the promoter of the gluconeogenesis gene fructose-1,6-biphosphatase (FBP1) is repressed by aberrant DNA and histone methylation that involves the repressive trimethylation of lysine 9 on histone 3 (H3K9me3)." (PMID 34572926, 2021). "It has been reported that Fbp1 exhibits pro‐oxidative effects on basal‐like breast cancer and that Fbp1‐expressing cells show a marked increase in ROS levels." (PMID 33960626, 2021). "We recently reported that several molecules, aldo-keto reductase 1 member B1 (AKR1B1), fructose-1,6-biphosphatase (FBP1), and urine diphosphate–galactose ceramide galactosyltransferase(UGT8) were associated with breast cancer aggressiveness." (PMID 34746019, 2021). "Recently, low expression of FBP1 is regarded as a potential prognostic factor for malignancies including gastric cancer, breast cancer, and lung cancer." (PMID 34363022, 2021). "Lastly, breast cancer tissues exhibited higher PIM2 and FBP1 Ser144 phosphorylation expression than normal, tumor-adjacent breast tissues, suggesting its importance for breast cancer progression." (PMID 32754266, 2020). "To investigate the potential relationships between FBP1 and PD-L1, we first silenced or overexpressed FBP1 to test PD-L1 expression in breast cancer cells." (PMID 32754266, 2020). "To study the clinical relevance of FBP1 Ser144 phosphorylation, we collected 20 breast cancer samples with paired surrounding normal breast tissues." (PMID 32754266, 2020). "The paradoxical suppression of PFKP and FBP1 by Snail suggested molecular subsets of different catabolic metabolism in breast cancer, leading us to further investigate metabolic-dependency based on breast cancer subtypes." (PMID 32927665, 2020). "In breast cancer, restoration of FBP-1 expression intensely inhibited glycolysis by catalyzing the function and silencing activity of HIF." (PMID 33256814, 2020). "Taken together, we conclude that FBP1 Ser144 phosphorylation leads to enhanced p65 transcriptional activity in breast cancer cells." (PMID 32754266, 2020). "In breast cancer patients, DNA methylation in the promoter region of FBP1 also decreased FBP1 expression in liver tissue." (PMID 29984231, 2018).
breast carcinoma (continued). "In basal-like breast cancer, FBP1 expression can be transcriptionally repressed by Snail1 to stimulate glycolysis and confer a metabolic advantage to cancer stem cells, and nearly all renal cell carcinomas deplete FBP1 to promote their aggressiveness." (PMID 29995892, 2018). "c-Myc, a crucial downstream factor of Wnt/β-catenin signalling, was found to be negatively correlated with the level of FBP1 in breast cancer cells." (PMID 29556139, 2018). "The Snail-G9a-Dnmt1 complex, which is critical for E-cadherin promoter silencing, was also responsible for the promoter methylation of FBP1 in basal-like breast cancer cells." (PMID 30429463, 2018). "FBP1, the rate-limiting enzyme in gluconeogenesis, is a critical modulator in breast cancer progression by altering glucose metabolism." (PMID 29262565, 2017). "Another study reported that the transcriptional factor Snail repressed fructose-1,6-bisphosphate (FBP1) gene expression, resulting in the induction of glycolysis in basal-like breast cancer cells undergoing EMT." (PMID 29403375, 2017). "Fructose-1,6-bisphosphatase (FBP1), a rate-limiting enzyme in gluconeogenesis, was reported to be a tumour suppressor in renal and breast cancer." (PMID 28240261, 2017). "The downregulation of fructose-1,6-biphosphatase (FBP1) by epigenetic mechanisms increased the rate of glycolysis but decreased the ROS level in basal-like breast cancer, resulting in the activation of β-catenin signaling to maintain CSCs." (PMID 26273424, 2015). "Recent studies indicated that, in basal-like breast cancer stem cells, overexpression of FBP1 enhanced oxidative phosphorylation and ROS production and decreased β-catenin signaling by promoting its dissociation from TCF4." (PMID 26273424, 2015). "In breast cancer cells, FBP1 and HIF-1α are oppositely expressed." (PMID 40100307, 2025). "Overexpression of FBP1 may directly inhibit cancer progress and migration in breast cancer and renal cell carcinoma by interacting with HIF structure." (PMID 40100307, 2025). "We therefore developed a new macrophage-specific SPP1 TAM signature (PLAUR, SLC11A1, BRI3, FBP1, C15orf48) using publicly available scRNA-Seq data from lung, colorectal and breast cancers and validated the signature using multiple independently published scRNA-Seq datasets." (PMID 41415295, 2025). "FBP1, the rate-limiting enzyme of gluconeogenesis, is generally considered a tumor suppressor and shows decreased expression in various tumors, such as renal, prostate, liver, and breast cancer." (PMID 36900384, 2023). "Moreover, UCP1 was reported to regulate the stemness of breast cancer stem cells through glycometabolism key enzyme FBP1 and ALDH 12, revealing various functions of UCP1 in the breast cancer process." (PMID 35541900, 2022). "Moreover, the abnormally high expression of fructose-bisphosphatase 1 (FBP1), a downstream glycolysis enzyme and tumor suppressor which was recognized as a glycolysis inhibitor inhibits the invasion and metastasis of breast cancer." (PMID 36072431, 2022). "Furthermore, a previous study reported the critical role of FBP1 in the metabolism of breast cancer cells." (PMID 35631492, 2022). "Likewise, the glycolytic activity of breast cancer cells can be promoted through the repression of the FBP1 and glucose-6-phosphate (G6P) genes by lysine demethylase 1A (LSD1)-dependent demethylation of specific activating histone methylation marks." (PMID 34572926, 2021). "High expression of FBP1 inhibits the growth, metastasis, and glycolysis of breast cancer." (PMID 33564363, 2021). "To examine this notion, we rescued FBP1 expression in FBP1-knockdown breast cancer cells." (PMID 32754266, 2020). "Interestingly, clustering analysis with PFKP and FBP1 revealed distinct breast cancer subtypes, and transcript abundance of the two genes were inversely correlated." (PMID 32927665, 2020).
breast carcinoma (continued). "As the ACC2 comprises a Snail target resulting in increased FAO, we speculated that an FBP1-loss subtype, such as TNBC, is accompanied by suppression of ACC2 in breast cancer to support efficient mitochondrial catabolic metabolism." (PMID 32927665, 2020). "Interestingly, PFKP and FBP1 are inversely correlated in clinical samples, indicating different metabolic subsets of breast cancer." (PMID 32927665, 2020). "While it has not been addressed directly, a similar inhibition of HIF-1α-mediated transcriptional regulation by FBP1 may exist in breast cancer." (PMID 30691108, 2019). "Expression of FBP1 is repressed in a number of cancers including breast cancer." (PMID 30691108, 2019). "These contradictory findings indicated that the prognostic value of FBP1 in breast cancer may be molecular type- and tissue type-dependent." (PMID 29556139, 2018). "In basal-like breast cancer, it has been demonstrated that the epithelial-mesenchymal transition (EMT) factor Snail can directly bind with the promoter of the gene encoding FBP1, leading to the down regulation of FBP1 expression." (PMID 28009990, 2017). "A previous study comparing basal and luminal subtypes of breast cancer demonstrated loss of the metabolic enzyme FBP1 in the more mesenchymal, basal subtype; however, inhibition of FBP1 alone was not sufficient to regulate EMT." (PMID 25379179, 2014). "While the inhibition of PFK-1 activity through glycosylation has been shown to promote the PPP and growth of cancer cells, loss of FBP1, whose activity directly opposes that of PFK-1 by converting F-1,6-P2 to F-6-P, has also been observed in human liver, colon, gastric and breast cancers." (PMID 24383451, 2014). "Bigl and colleagues examined FBP1 expression in several types of breast cancer and found it to be up-regulated in invasive lobular carcinoma when compared to normal tissue but down-regulated in other tumor types suggesting a variable role depending on tumor type." (PMID 20860831, 2010). "Moreover, beyond its role in inhibition of glycolysis, some studies have reported that overexpressed FBP1 may directly suppress tumor growth and migration in breast cancer and renal cell carcinoma by interacting with the hypoxia-inducible factor (HIF) domain." (PMID 34363022, 2021). "The data showed that FBP1 could bind to p65 in breast cancer." (PMID 32754266, 2020). "The luminal types of breast cancer consist of the pentose phosphate pathway (PPP) subset by suppression of PFKP while the basal-like subtype (also known as triple negative breast cancer, TNBC) mainly utilizes glycolysis and mitochondrial fatty acid oxidation (FAO) by loss of FBP1 and ACC2." (PMID 32927665, 2020). "Recent studies have demonstrated that low or absent expression levels of FBP1 was a critical oncogenic event in epithelial-mesenchymal transition and might be associated with reduced disease-free survival in basal-like breast cancer." (PMID 29262565, 2017). "Recently, a study showed that overexpressed FBP1 inhibited HIF-1α protein expression under hypoxic conditions, related to cell metabolism in breast cancer cells." (PMID 40419474, 2025). "In basal-like breast cancer, the Snail-G9a-DNMT1 complex induces methylation of the FBP1 promoter, leading to down-regulation of FBP1." (PMID 38349431, 2024). "Recently, we have reported several enzymes, such as fructose-1,6-biphosphatase (FBP1), urine diphosphate-galactose ceramide galactosyltransferase (UGT8) and phospholipid scramblase 1 (PLSCR1), were tightly correlated with breast cancer aggressiveness." (PMID 35526049, 2022). "In breast cancer, the HMGB2 is regulated with ER, LDHB, and FBP1 to promote the endocrine therapy resistance and tumorigenesis of tumor cells." (PMID 35962344, 2022).